UBE3D (ubiquitin protein ligase E3D)
Description:
E3 ubiquitin-protein ligase which accepts ubiquitin from specific E2 ubiquitin-conjugating enzymes, and transfers it to substrates, generally promoting their degradation by the proteasome. Independently of its E3 ubiquitin-protein ligase activity, acts as an inhibitor of CPSF3 endonuclease activity by blocking CPSF3 active site.
Synonyms: C6orf157; H10BH; UBE2CBP; DKFZp434A1520; YJR141W
Tractability: PROTAC: UniProt records ubiquitination sites on it; ubiquitination databases record sites on it.
Gene: Protein-coding gene on chromosome 6 (82,892,390 to 83,065,841, reverse strand). Ensembl gene ENSG00000118420.
Subcellular location: Cytoplasm
Subcellular location (Human Protein Atlas): Rods & Rings
Pathways (Reactome):
Immune System: Antigen processing: Ubiquitination & Proteasome degradation
Gene Ontology:
Molecular function: cyclin binding; protein binding; ribonuclease inhibitor activity; ubiquitin protein ligase activity; ubiquitin-like protein conjugating enzyme binding; ubiquitin conjugating enzyme binding
Biological process: protein autoubiquitination; protein monoubiquitination; protein polyubiquitination; proteasome-mediated ubiquitin-dependent protein catabolic process; protein ubiquitination
Cellular component: cytoplasm; cytosol; ubiquitin ligase complex; nucleus
Genetic constraint (gnomAD): Loss-of-function variants: 35 observed, 40.22 expected, observed/expected ratio (o/e) 0.87, 90% interval 0.66 to 1.15. The upper end of that interval is the gene's LOEUF score, 1.15, which puts it in group 5 of 6, group 1 being the genes least tolerant of losing a copy. Missense variants: 394 observed, 444.02 expected, observed/expected ratio (o/e) 0.89, 90% interval 0.82 to 0.96. Synonymous variants: 173 observed, 171.62 expected, observed/expected ratio (o/e) 1.01, 90% interval 0.89 to 1.14.
Homologues: Orthologues: chimpanzee UBE3D (98% identical), macaque UBE3D (94% identical), dog UBE3D (82% identical), pig UBE3D (81% identical), guinea pig UBE3D (76% identical), mouse Ube3d (74% identical), rat Ube3d (72% identical), rabbit UBE3D (63% identical), tropical clawed frog ube3d (44% identical), zebrafish ube3d (37% identical), Caenorhabditis elegans Y71H2AM.3 (20% identical).
Diseases named in the same sentence as UBE3D in open-access papers:
UBE3D is named in the same sentence as 8 diseases in open-access papers, as found by Europe PMC text mining. Sharing a sentence is not in itself a finding about the gene and the disease. The quoted sentences say what the papers report.
age-related macular degeneration (1 paper, 2025). Age-related loss of vision in the central portion of the retina (macula), secondary to retinal degeneration. "Recently, UBE3D has been identified as an important protein associated with age-related macular degeneration in humans, and the retina phenotype can be replicated in Ube3d+/− mice." (PMID 40075082, 2025).
diabetes (1 paper, 2022). "Other migration-associated mutations were found in genes determining obesity and diabetes in human, mice, sheep, and cattle (e.g. gene UBE3D and TCF7)." (PMID 35143486, 2022).
prostate carcinoma (1 paper, 2023). A carcinoma that arises from epithelial cells of the prostate gland. "Patients with lower UBE3D abundance are at risk for the onset and early development of aggressive prostate cancer." (PMID 38099500, 2023). "UBE3D is frequently deleted in advanced prostate cancer, and its expression is also varied substantially in patients at early disease stages." (PMID 38099500, 2023). "Notably, UBE3D deletion was frequently present in different cohorts, indicating that the correlation of UBE3D with prostate cancer is not limited to East Asians but involves different ethnicities." (PMID 38099500, 2023).
retinal degeneration (1 paper, 2023). Degeneration of the retina. "In a zebra fish embryo model, low expression of UBE3D promotes oxidative damage and inflammatory reactions, and its knockdown leads to delayed eye development, reduced eye size, apoptosis, and overall retinal degeneration." (PMID 36727109, 2023).
tumor (1 paper, 2023). "UBE3D was found in our studies to regulate 3βHSD1 homeostasis, regardless of 3βHSD1 genotype, and negatively correlate with tumor aggressiveness in different databases." (PMID 38099500, 2023). "UBE3D regulates 3βHSD1 homeostasis, and equilin antagonizes the development of tumor with potent 3βHSD1 activity." (PMID 38099500, 2023). "Tumors with UBE3D overexpressed shrank as indicated by tumor weight." (PMID 38099500, 2023). "The effect of UBE3D on DHEA-mediated tumor growth was then further tested in vivo." (PMID 38099500, 2023). "Together, these data demonstrate that UBE3D regulates 3βHSD1 homeostasis and consequently affects DHEA utilization and tumor aggressiveness." (PMID 38099500, 2023).
UBE3D also shares sentences with these, for which no sentence is quoted: cancer (1 paper); myopathy (1); Obesity (1).